PIK3R1 (phosphoinositide-3-kinase regulatory subunit 1)
Diseases named in the same sentence as PIK3R1 in open-access papers (continued):
Sharing a sentence is not in itself a finding about the gene and the disease.
cancer (continued). "Some cancers have activating mutations in the PI3K regulatory subunit P85α (encoded by PIK3R1)." (PMID 36672927, 2023). "Somatic mutations in PIK3R1 are often associated with increased PI3K/Akt signalling in cancer." (PMID 36522480, 2023). "Indeed, loss-of-function disruptions in PIK3R1 are frequent in cancers, including copy number loss and truncation or point mutations." (PMID 32385243, 2020). "Emerging evidence has indicated the functional consequences of PIK3R1 loss in cancers." (PMID 30755611, 2019). "PIK3R1 is the 11th most commonly mutated gene across cancer lineages in TCGA database." (PMID 31402930, 2019). "Moreover, inhibition by ARQ 092 and ARQ 751 was more prevalent in cancer cell lines containing PIK3CA/PIK3R1 mutations compared to those with wt-PIK3CA/PIK3R1 or PTEN mutations." (PMID 26469692, 2015). "Mutations of PIK3R1 are present at a low prevalence in multiple types of cancer." (PMID 25227228, 2014). "Mutations of PIK3R1, encoding p85α, have been reported in some cancers." (PMID 24367658, 2013). "In several cancer types, PIK3R1 experiences copy number loss, leading to the activation of downstream signaling molecules that promote cancer development, suggesting that the occurrence of PIK3R1 copy number deletion may be a key indicator linked to poor cancer prognosis." (PMID 40657399, 2025). "Higher levels of promoter methylation of PIK3R1 have been observed across various cancer types, and this methylation is positively correlated with gene expression levels in multiple probes within the promoter region." (PMID 40657399, 2025). "Network-based interactome analysis identified PIK3R1, SRC, and ESR1 as highly connected nodes within cancer-associated signaling networks." (PMID 40649280, 2025). "The samples were divided into those with low and high PIK3R1 mRNA levels according to the median expression in the cancer group (0.0989) (n = 72 in each group)." (PMID 39858051, 2025). "The loss of PIK3R1 was more frequently observed in advanced FIGO IIIC-IV stages (34.8%, 47/135) than in FIGO stage I-IIIB cancers (14.5%, 9/62, p = 0.003)." (PMID 39858051, 2025). "Low PIK3R1 expression was more frequent in cancers with PIK3CA amplifications than those with PIK3CA WT tumors (64%, 14/22 vs. 38%, 24/64, p = 0.033)." (PMID 39858051, 2025). "Overall, PIK3R1 emerges as a target of multiple miRNAs and plays a significant role in the initiation and progression of various cancers." (PMID 40657399, 2025). "The previous study on PIK3R1/2 gene expression in various malignant tumors has shown that PIK3R2 is highly expressed in most tumors and is associated with poor prognosis in certain types of malignancies." (PMID 40504311, 2025). "The PIK3R1 gene encodes the class IA PI3K regulatory subunit p85α, which is frequently altered in cancer." (PMID 40657399, 2025). "In animal models of cancer, liver-specific knockout of PIK3R1 has also been shown to increase PI3K pathway activation, thereby facilitating tumorigenesis." (PMID 40657399, 2025). "Tumors with PIK3R1 deletion and underexpression shared similar phenotypes of high-grade carcinomas (p = 0.003 and p = 0.025, respectively)." (PMID 39858051, 2025). "We found that a small number of genes (e.g., RET, RECQL4, CUX1, FGFR4, PIK3R1, FGFR3, and GNAS) had some co-occurring variants per patient in different cancer types." (PMID 38637555, 2024). "Key genes such as COL1A1, COL4A1, PIK3CA, PIK3R1, and mTOR were found to be overexpressed, correlating with increased cancer aggressiveness." (PMID 39850811, 2024).
cancer (continued). "Numerous studies have demonstrated that phosphatidylinositol 3-kinase (PI3K) genes, particularly PIK3CA and PIK3R1, have an oncogenic effect and are involved in various types of human cancers." (PMID 39409902, 2024). "Some PIK3R1 mutations reduce basal inhibition of catalytic subunits, usually due to disruption of the inhibitory inter-SH2 domain, and are found in cancers and vascular malformations with overgrowth." (PMID 38077044, 2024). "In conclusion, we identified PIK3R1, CCND1, TERF2IP, SLC25A4, CAPN2, and TXN as potential markers associated with both cancer and MN." (PMID 38846934, 2024). "Phosphatidylinositol-3-kinase regulatory subunit 1 (PIK3R1) exhibits low expression levels in the majority of cancers and is believed to function as a cancer suppressor." (PMID 38846934, 2024). "In detail, BRD9 was located together with other known cancer dependencies, including PIK3R1, EZH2, and FBXW7, whereas SF3B1 had a very high efficacy but low selectivity." (PMID 39261602, 2024). "The regulatory subunits (p85) of PI3K also exhibited significant roles; p85α (PIK3R1) acted as a tumor suppressor with reduced expression in cancer, whereas p85β (PIK3R2) functioned as an oncogene, showing heightened expression in cancers." (PMID 38287309, 2024). "Carcinomas with apocrine differentiation exhibit a distinct set of somatic alterations, including mutations in PIK3CA, PIK3R1, and AKT1, indicating that activation of the PI3K pathway plays a crucial role in the molecular pathogenesis of the disease." (PMID 39272660, 2024). "The results indicated that SPP1 is a cancer promoter (oncogene), while PECAM1 and PIK3R1 are cancer suppressor genes." (PMID 36688087, 2023). "The PI3K/AKT/mTOR pathway is commonly dysregulated in human cancer, due to mutation of dominantly acting oncogenes (PIK3CA, AKT isoforms, MTOR), inactivation of tumor suppressor genes (PTEN, TSC1, TSC2, PIK3R1), and amplification of growth-promoting oncogenes." (PMID 37909334, 2023). "It is important to note that two genes, FOS (AP-1) and PIK3R1, are found in “PD-L1 expression and PD-1 checkpoint pathway in cancer”, while the “endocrine resistance pathway” is activated by hypoxia induction." (PMID 37240068, 2023). "In cancer, changes in the PIK3R1 gene result in alteration of the regulatory subunit of the enzyme which results in loss of control in the enzyme’s activity." (PMID 37687413, 2023). "PIK3R1/p85a is the most abundant isoform in normal tissues but its expression is reduced in cancer suggesting that it regulates cell proliferation." (PMID 37174557, 2023). "The reduction in expression of Pik3r1 in the cancer cell population suggested a role for increased PI3K/AKT signaling in DES cancer formation." (PMID 37856394, 2023). "In this large, real-life pan-cancer patient cohort, our results indicate that PIK3CA/PIK3R1 mutations are widely spread, and plead in favour of evaluating the efficacy of PI3K inhibitors outside of ER+/HER2− mBC and outside of hotspot mutations." (PMID 36934165, 2023). "Overall, PIK3R1 expression was lower in most cancers while PIK3R2 was higher compared with the corresponding control tissue." (PMID 35395865, 2022). "In line with this, genes promoting cancer development and cell apoptosis (Ccnd1, Fdps, and Pik3r1) were lower expressed in M-moC than in F-moC, and MO reduced the expression in females only." (PMID 36195702, 2022).
cancer (continued). "Our findings also suggested PIK3R1 and PIK3R2 expression both had positive correlations with cancer-associated fibroblasts in the majority of tumors." (PMID 35395865, 2022). "Meanwhile, it suggested that besides gene mutations, decreased or increased mRNA expression levels of PIK3R1 and PIK3R2 are supposed to be considered in clinical management of cancer." (PMID 35395865, 2022). "Fifteen (11.9%) cancers harbored 16 PI3K pathway mutations: PIK3CA (n = 7), AKT2 and RICTOR (n = 3 each), PTEN, PIK3C2B, and PIK3R1 (n = 1 each)." (PMID 36124727, 2022). "We also presented comprehensive evidence of the relationship between PIK3R1 as well as PIK3R2 and immune infiltration levels of six immune cells and cancer-associated fibroblasts in TCGA tumors." (PMID 35395865, 2022). "Through our pan-cancer analysis of PIK3R1 and PIK3R2, this study revealed the important role of their aberrant expression in carcinogenesis and patient survival that warrant further investigation." (PMID 35395865, 2022). "Somatic mutations hit genes wired to cancer proliferation, survival, and migration pathways, in the first place Ras/MAPK, PI3K-AKT, in addition to JAK/STAT (PIK3R1 and PTK2)." (PMID 32321919, 2020). "According to the function of the modules and the degree value of the nodes in the GBC-related FI network, we chose PIK3R1 (degree = 8) as a functional hub gene in Module 0, which was the most related to classical cancer pathways, to validate expression in GBC." (PMID 31119098, 2019). "PIK3R1 alterations are found at high frequency in several cancer types, including: endometrial (29%, 172/586), glioblastoma (7%, 41/593), colorectal (6%, 38/594) and prostate (6%, 4/70)." (PMID 30650664, 2019). "PIK3R1 expression is reduced in some cancer types as compared to that in their corresponding normal tissue, including cancers of the ovary, prostate, breast, lung, liver and kidney." (PMID 30650664, 2019). "The poor survival samples also over-expressed CTNNB1 and SOX4 and under-expressed PIK3R1 and TP63, all of which have been linked to tumorigenesis in other cancers." (PMID 29484115, 2018). "Mutations of PIK3R1 and/or PIK3R2 are also found in cancer cells resulting in the altered expression of PI3K." (PMID 29755656, 2018). "Second, we noted Cluster 21 is comprised of the two phosphatidylinositol 3-kinase signaling/Akt (PI3K) regulating genes, PIK3R1 and PTEN, both frequently mutated across 12 cancer types in The Cancer Genome Atlas (TCGA)." (PMID 28315521, 2017). "We genotyped five potentially functional PIK3R1 and mTOR SNPs in 1116 esophageal squamous cell cancer (ESCC) patients and 1117 cancer-free controls to assess their associations with ESCC risk." (PMID 25654238, 2015). "Other large CNA genes gained or lost in the correct direction to drive cancer are PIK3R1 and CASP3 in BACA, and NRAS and CCND1 in CLAC." (PMID 26560147, 2015). "Vice versa, up-regulation of RPS6 and down-regulation of PTEN and PIK3R1 in TSCCs is typical of aggressive cancers." (PMID 24427739, 2013). "Some of these mutations are considered clinically actionable, such as alterations in the PI3K pathway (loss of PTEN or PIK3R1, amplification of PIK3CA) for which targeted therapies are currently in clinical trials in several cancer types." (PMID 23441165, 2013). "For cancer genes which have been reported to have somatic or germline mutations in EOC, 3 were found to harbor copy deletions in serous histotype: PIK3R1, BRCA1, and STK11." (PMID 23078675, 2012).
cancer (continued). "PIK3R1 is a regulatory subunit of the phosphoinositide-3-kinase, which is a protein known to be involved in insulin actions, cancer signaling, and cytokine signaling." (PMID 23281828, 2012). "In the cancer pathway cluster, CASP9 and PIK3R1 are both involved in 7 different cancer pathways, while SOS1 and TCF7L2 are both involved in 5 different pathways." (PMID 23281828, 2012). "Single-strand conformational polymorphism/heteroduplex analysis revealed the presence of somatic mutations in the gene for the p85α regulatory subunit of PI3K (PIK3R1) in primary human colon and ovarian tumors and cancer cell lines." (PMID 19384426, 2007). "Based on the ceRNA hypothesis, our study identified putative downstream mRNAs regulated by miRNAs, such as FGF2, MCFD2, and PIK3R1, which are often reported to exert oncogenic functions in various cancers, consistent with the findings of most previous studies." (PMID 41141624, 2025). "The 5q13.1 region containing PIK3R1 is frequently lost in breast (23%) and prostate (24%) cancers." (PMID 39858051, 2025). "In this study, we found that PIK3R1 overexpression promoted decreased IκBa phosphorylation and increased IκBa; then, IκBa bound to more NFκB subunits to inactivate NFκB, and the cancer-promoting effect of NFκB was significantly reduced, which is consistent with the findings of previous studies." (PMID 39949569, 2025). "Furthermore, hsa_circ_0087104 enhances PIK3R1 expression in EC by suppressing miR-542-3p, resulting in decreased migration and invasion of cancer cells." (PMID 41141624, 2025). "We also discuss the role of epigenetic alterations in PIK3R1 in cancer initiation and progression." (PMID 40657399, 2025). "The accumulating body of evidence related to genetic aberrations in PIK3R1 and corresponding cancer markers reinforces the notion that targeting the aberrant PIK3R1 pathway could be advantageous for anticancer therapy." (PMID 40657399, 2025). "Consequently, the methylation level of PIK3R1 is positively correlated with expression levels and is closely related to clinical data from cancer patients, establishing it as a promising cancer biomarker." (PMID 40657399, 2025). "Thus, PIK3R1 deletion activates downstream AKT signaling and facilitates tumorigenesis through various mechanisms across different cancer types, which is associated with unfavorable prognoses for patients." (PMID 40657399, 2025). "In most types of cancer, PIK3R1 is in a low expression state." (PMID 39771106, 2024). "The KEGG enrichment analysis of RNA sequencing results on TNBC-specific CTLs indicated that PD-L1 expression and PD-1 checkpoint pathway in cancer was co-inhibited by IL23 and PD-1 mAb through downregulating PIK3R1, which encodes the regulatory subunit p85α of class IA PI3Ks." (PMID 38902343, 2024). "Increasing research has shown that PIK3R1 plays a vital role in human cancer development." (PMID 37240068, 2023). "Type I PI3K is a heterodimer, consisting of PIK3R1 and PIK3CA, closely associated with cancer." (PMID 36654811, 2023). "The pan-cancer study comprehensively investigated the gene expression, genetic alteration, DNA methylation, and prognostic significance of PIK3R1 and PIK3R2 in 33 different tumors based on the TIMER, GEPIA, UALCAN, HPA, cBioPortal, and Kaplan–Meier Plotter database." (PMID 35395865, 2022). "PIK3R1 encodes the p85α regulatory subunit of the PI3K enzyme, which is involved in cancer growth." (PMID 35482141, 2022). "The results indicated that PIK3R1 expression was positively associated with the infiltration level of immune cells in the majority of tumors, by contrast, PIK3R2 expression was negatively associated with immune infiltration level in most cancer." (PMID 35395865, 2022).
cancer (continued). "In conclusion, PCBs can interfere with thyroid hormone dysfunction by regulating MAPK3, MAPK1, RXRA, PIK3R1, and other potential targets, as well as the cancer pathway, PI3K-Akt signaling pathway, thyroid hormone signaling pathway, prolactin signaling pathway, and FoxO signaling pathway." (PMID 36203481, 2022). "Moreover, not only mutations, downregulation of PIK3R1 and upregulation of PIK3R2 were found to be detrimental to the survival of most cancer patients as well." (PMID 35395865, 2022). "Studies have shown that PIK3R1 was responsible for chemotherapy resistance in many cancers." (PMID 35582195, 2022). "PIK3R1 variants that fail to inhibit p110α activity, usually by disruption of the inter-SH2 domain, cause constitutive PI3K pathway activation, and are enriched in cancers, albeit much less commonly than PIK3CA variants." (PMID 34040190, 2021). "miR‐21‐5p plays the role of oncogene in human cancers, according to the prediction of miranda, targetscan, encori and pictar, and we found there was a miR‐21‐5p binding site in the 3'noncoding region of PIK3R1 mRNA." (PMID 34741385, 2021). "Importantly, we firstly found MSC‐derived exosomal miR‐21‐5p promotes OS proliferation and invasion by targeting PIK3R1 and activity of cancer‐related PI3K/Akt/mTOR signalling pathway." (PMID 34741385, 2021). "In addition, copy number loss, truncation or point mutations of phosphoinositide-3-kinase regulatory subunit 1 (PIK3R1/p85α) are frequent events in some types of cancer." (PMID 34419139, 2021). "Several studies reported a down-regulation of PIK3R1 in many human cancers." (PMID 33670375, 2021). "We supposed that PIK3R1 was an oncogene in malignant tumors." (PMID 32817745, 2020). "There are three lncRNAs located close together in the interaction network: NONMMUG034109, NONMMUG021221, and NONMMUG008287; these are involved in the regulation of the mRNA expression of a large number of cancer-related genes, such as Pik3r1, Gulp1, Chrdl1, and Crebaf." (PMID 31947603, 2020). "Interestingly, miR-487a stimulates cancer cell proliferation via PIK3R1-mediated AKT signaling and promotes metastasis via SPRED2-induced mitogen-activated protein kinase signaling in HCC." (PMID 32377460, 2020). "PIK3CA and PIK3R1 are centrally involved in several cancers." (PMID 32962181, 2020). "PIK3R1 has been shown to play important roles in many developmental processes, including cancer." (PMID 30497511, 2018). "We could find protein expression level of PIK3R1 in both the normal cell and the cancer cell using Human Protein Atlas." (PMID 27490120, 2016). "From these evidences, we could make hypothesis that cancer-specific high expression of PIK3R1 increases activation of PIK3CA and as a result, negatively regulated apoptotic function cause cancer in breast." (PMID 27490120, 2016). "These genes include those mutated in other cancer types and bound with HCV proteins (e.g. PIK3R1 and EP300), genes interfacing with alternative partner groups (e.g. YWHAZ), and genes manifesting both differential co-expression and differential expression (e.g. ESR1)." (PMID 24564909, 2013). "Also, PIK3R1 a gene overexpressed in advanced stages has been suggested as a potential therapeutic target in several cancers." (PMID 24403257, 2013). "However, the role of PIK3R1 or PIK3R2 in some other cancers and whether PIK3R1 or PIK3R2 can play a role in the pathogenesis of different tumors through certain common molecular mechanisms remains to be explored." (PMID 35395865, 2022). "Gene mutations in PIK3CA, PIK3R1, and PTEN are commonly detected in type I EC and may lead to activation of the PI3K/Akt/mTOR pathway, which is central to cell growth and proliferation in cancer." (PMID 35902869, 2022).